JAK2 (Janus kinase 2)
Diseases named in the same sentence as JAK2 in open-access papers (continued):
Sharing a sentence is not in itself a finding about the gene and the disease.
leukemia (continued). "For example, in ALL or AML, JAK2 inhibitors such as ruxolitinib can help reduce leukemia cell resistance to chemotherapy by disrupting the aberrant signaling that sustains leukemia cell survival." (PMID 40486651, 2025). "The continued success of JAK2 inhibitors in pediatric leukemia will depend on the conduct of large-scale, well-designed clinical trials." (PMID 40486651, 2025). "Access to JAK2 inhibitors and cutting-edge treatments remains a challenge in resource-limited settings, where pediatric leukemia is often diagnosed at advanced stages." (PMID 40486651, 2025). "One such critical genetic factor that has emerged as a potential driver of pediatric leukemia is the Janus kinase 2 (JAK2) gene." (PMID 40486651, 2025). "By targeting JAK2, these inhibitors aim to block the aberrant signaling that drives leukemogenesis, offering a potential therapeutic option for treating JAK2-driven pediatric leukemia." (PMID 40486651, 2025). "Ensuring equitable access to JAK2 inhibitors and other emerging therapies is essential for improving outcomes in pediatric leukemia, particularly in underserved populations." (PMID 40486651, 2025). "For leukemia treatment, selective JAK2 inhibitors are preferred because they provide more targeted inhibition, minimizing the risk of off-target effects on normal hematopoiesis." (PMID 40486651, 2025). "Continued research and innovation are essential to optimize the use of JAK2-targeted therapies, address existing challenges, and improve outcomes for pediatric leukemia patients." (PMID 40486651, 2025). "After 2 weeks of doxycycline chow, mice with JAK2 KO cells had a significantly reduced leukemia burden in bone marrow, spleen and peripheral blood, as well as decreased spleen weight." (PMID 40470252, 2025). "These inhibitors work by blocking the kinase activity of JAK2, preventing its downstream signaling and inhibiting leukemia cell proliferation." (PMID 40486651, 2025). "The role of JAK2 in pediatric leukemia represents a critical area of research with immense therapeutic potential." (PMID 40486651, 2025). "In these studies, ruxolitinib has been shown to inhibit leukemia cell proliferation and induce apoptosis in JAK2-mutant leukemia models." (PMID 40486651, 2025). "Increasing awareness among healthcare providers about the potential of JAK2-targeted therapies and ensuring that pediatric leukemia is diagnosed early will be key to improving survival rates in low-resource settings." (PMID 40486651, 2025). "In summary, while CBFA2T3::GLIS2 leukemia remains a difficult-to-treat disease, we have validated JAK2 as a selective dependency offering a new possibility for precision medicine in this very high-risk AML subset." (PMID 40470252, 2025). "Future research should explore the potential for epigenetic modulators in combination with JAK2 inhibitors to alter the leukemia epigenome, potentially restoring normal cell differentiation and enhancing therapeutic responses." (PMID 40486651, 2025). "By inhibiting JAK2, the immune surveillance system becomes more effective in recognizing and destroying leukemia cells, even in the presence of immunosuppressive factors in the TME." (PMID 40486651, 2025). "By targeting the JAK-STAT signaling pathway, which is often dysregulated in leukemic cells, JAK2 inhibitors can overcome multiple layers of drug resistance in leukemia, improving treatment outcomes." (PMID 40486651, 2025). "The growing understanding of JAK2’s role in leukemia pathogenesis has important implications for the development of novel therapeutic approaches." (PMID 40486651, 2025). "The aberrant activation of JAK2 leads to the dysregulation of immune responses, further complicating leukemia treatment." (PMID 40486651, 2025). "In pediatric leukemia models, JAK2 inhibitors have demonstrated the ability to reduce leukemia cell growth and improve survival rates." (PMID 40486651, 2025).
leukemia (continued). "Combination therapies, which involve the use of multiple therapeutic agents, are increasingly being explored to enhance the efficacy of JAK2 inhibitors in the treatment of pediatric leukemia." (PMID 40486651, 2025). "Despite the promising potential of JAK2 inhibitors in treating pediatric leukemia, several challenges hinder their widespread application and efficacy in clinical practice." (PMID 40486651, 2025). "DNA methylation, histone modification, and non-coding RNA expression are important factors influencing JAK2-mediated signaling pathways in leukemia." (PMID 40486651, 2025). "Future research should focus on understanding how the TME contributes to leukemia progression and resistance to JAK2 inhibitors." (PMID 40486651, 2025). "While JAK2 inhibitors have shown promise in treating other malignancies, their application in pediatric leukemia has yet to be fully explored." (PMID 40486651, 2025). "While JAK2 inhibitors offer promising therapeutic potential for pediatric leukemia, a number of critical steps must be taken to optimize their use and improve clinical outcomes." (PMID 40486651, 2025). "Increased collaboration between research institutions, pharmaceutical companies, and clinical centers is essential to accelerate the development and testing of JAK2 inhibitors in pediatric leukemia." (PMID 40486651, 2025). "Preclinical models further demonstrate that JAK2 inhibition suppresses Th1 and Th17 polarization, mitigates inflammatory tissue damage, and preserves graft-versus-leukemia (GvL) activity." (PMID 40722603, 2025). "The JAK2 inhibitor fedratinib is active against wild-type and mutated JAK2 and also FLT3, suggesting potential utility in leukemias harboring activating mutations in both genes." (PMID 40247105, 2025). "Moreover, combining JAK2 inhibitors with allogeneic stem cell transplantation (HSCT) could be a strategy to target MRD while reducing the risk of post-transplant relapse in high-risk pediatric leukemia patients." (PMID 40486651, 2025). "By specifically targeting JAK2-driven signaling, inhibitors can reduce the survival and self-renewal capacity of leukemia stem cells, preventing them from contributing to MRD and relapse." (PMID 40486651, 2025). "The development of JAK2 inhibitors represents a significant advancement in the treatment of pediatric leukemia, but several areas remain for improvement and further exploration." (PMID 40486651, 2025). "Efforts should be made to ensure equitable access to JAK2-targeted therapies in resource-limited settings, where pediatric leukemia is often diagnosed at advanced stages." (PMID 40486651, 2025). "A key advantage of JAK2 inhibitors in pediatric leukemia is their potential to specifically target leukemia cells while sparing normal hematopoietic cells." (PMID 40486651, 2025). "In parallel, emerging combination strategies involving JAK2 inhibitors and novel biologics show promise in enhancing immune tolerance while preserving graft-versus-leukemia (GvL) effects." (PMID 40722603, 2025). "This review is justified by the need to bridge the gap between existing preclinical and clinical data, focusing on the mechanisms of JAK2 involvement in pediatric leukemia and evaluating the potential of JAK2 inhibitors as targeted therapies for children." (PMID 40486651, 2025). "JAK2 mutations can activate STAT3 and STAT5, transcription factors that promote the expression of immune checkpoint molecules, such as PD-L1, on leukemia cells." (PMID 40486651, 2025). "JAK2 inhibitors can be used to enhance the effectiveness of epigenetic therapies by modifying the epigenetic landscape of leukemia cells." (PMID 40486651, 2025). "Given the complex nature of pediatric leukemia and the potential for drug resistance, combination therapies are likely to play a pivotal role in overcoming the limitations of JAK2 inhibitors." (PMID 40486651, 2025).
leukemia (continued). "Additionally, combining JAK2 inhibitors with IDH inhibitors (targeting isocitrate dehydrogenase mutations in leukemia) or TKIs (such as imatinib in CML) could provide a comprehensive treatment approach that targets both the JAK-STAT pathway and other critical oncogenic drivers in pediatric leukemia." (PMID 40486651, 2025). "By targeting the JAK2 pathway, these inhibitors can restore normal cell signaling, reduce leukemia cell survival, and enhance the sensitivity of leukemia cells to chemotherapy." (PMID 40486651, 2025). "The sensitivity of these resistant variants towards the type II JAK2 inhibitor CHZ-868 indicates that this mode of type II JAK2 inhibition is a potential therapeutic approach against ruxolitinib refractory leukemia." (PMID 39091915, 2024). "JAK2 and JAK3 are associated with the pathogenesis of leukemia and common lymphoid-derived illnesses." (PMID 36677654, 2023). "JAK2 negatively regulates β-TrCP activity in both human leukemia Jurkat cells and human erythroleukemia HEL cells." (PMID 37686524, 2023). "We found that JAK2 is highly correlated with the NOTCH pathway, which has been found to act as a tumour suppressor in leukaemia due to the large expansion of GMP cells after loss of NOTCH signalling." (PMID 36192425, 2022). "Childhood leukaemia study groups have focused on augmenting chemotherapy in combination with either Janus kinase 2 (JAK2) specific drugs, such as ruxolitinib, or ABL/platelet-derived growth factor receptor (PDGF-R) inhibitors, such as imatinib or dasatinib." (PMID 35186828, 2021). "As JAK3 mutants are dependent on JAK1 signaling for their cellular transformation, it is possible to use both JAK1/JAK2 and JAK3‐selective inhibitors in JAK3 mutation–positive leukemia." (PMID 35846099, 2021). "For our study, we concluded leonurine exerted its anti-leukemia effect at least partially by suppressing JAK2/STAT3 signaling pathway." (PMID 33935775, 2021). "Of note, ALL-SIL, MOLT-4 and RPMI-8402 cell lines showed a JAK1/2-STAT6 activation profile close to patients with worse prognosis as well as high levels of JAK2 Y1007-1008 compared to good prognosis patients and to the other leukemia cell lines." (PMID 34359628, 2021). "It has recently been shown that JAK2 inhibitor, AG490, causes the dephosphorylation of STAT3 and enhances cytotoxic activity of conventional chemotherapeutics in leukemia cells." (PMID 33807148, 2021). "Taken together, leonurine exerts significant anti-leukemia efficacy in CML by regulating miR-18a-5p/SOCS5/JAK2/STAT3 axis." (PMID 33935775, 2021). "Similar to JAK1 and JAK2 mutations, the most prevalent mutations in JAK3: M511I, A573V, and R657Q can drive several types of leukemia." (PMID 33672930, 2021). "More recently, the gain-of-function mutations in JAK1, JAK2, and JAK3 were identified in various leukemia subtypes." (PMID 34439155, 2021). "In cell-based assays, the suppression of Jak2 and Stat5 phosphorylation was documented within 30 min of compound administration to Jak2V617F-positive leukemia cells." (PMID 34680353, 2021). "In PMF, survival (either overall or leukemia free) is inferior in the JAK2 mutant patient population (as compared to MPL or CALR mutant patients; although triple negative, or 3N, PMF shows even worse survival)." (PMID 34140953, 2021). "The anti-leukemia activity of leonurine was illustrated by regulating miR-18a-5p/SOCS5/JAK2/STAT3 axis." (PMID 33935775, 2021). "As a multi-kinase inhibitor, TG02 potently inhibits the CDKs, as well as kinases that are well known for the pathogenesis of leukemia, such as JAK2 and FLT329." (PMID 33714981, 2021). "Previous reports showed that combined targeting of BCR-ABL1 and JAK2 using dasatinib and ruxolitinib, respectively, reduced leukemia engraftment and prolonged survival." (PMID 32581241, 2020).
leukemia (continued). "Inhibition of Bcr-Abl was reported to result in downregulation of STAT3 via JAK and MEK pathways, and ponatinib has been reported to inhibit phosphorylation of JAK2 both in BaF3/T315I cells in vitro and in leukemia models in vivo." (PMID 30959969, 2019). "Strikingly, a significant positive enrichment for the MYC gene signature was apparent in Eμ-Crlf2/Jak2R683G leukemia cells with chronic Jak2 depletion across multiple data sets (FDR < 0.01)." (PMID 29907650, 2018). "All Dox-treated (Jak2-off) recipient mice harboring Jak2 knockdown-persistent cells exhibited a delay in leukemia progression and conferred a significant survival benefit over the untreated (Jak2-on) cohort." (PMID 29907650, 2018). "Using our unique GEMMs of human JAK2 mutant B-ALL, we next assessed the critical importance of Jak2 for leukemia maintenance in vivo." (PMID 29907650, 2018). "Splenic Eμ-Crlf2/mutant Jak2 leukemia cells expressed GFP (surrogate readout of mutant Jak2 expression) and elevated cell surface Crlf2." (PMID 29907650, 2018). "This indicates that enhanced signaling through c-Myc in Eμ-Crlf2/Jak2R683G leukemia cells following chronic Jak2 depletion is mediated by enhanced c-Myc protein levels in the absence of any increase in mRNA levels." (PMID 29907650, 2018). "We next analyzed the signaling perturbations by JAK2 and mTOR inhibitors in the leukemia cells (gated on hCD19 by flow cytometry) collected from the murine spleens." (PMID 29487712, 2018). "We have no biochemical or molecular evidence to suggest that JAK/STAT signaling had been restored in leukemias with sustained inhibition or depletion of JAK2." (PMID 29907650, 2018). "Here, we developed genetically engineered mouse models (GEMMs) of CRLF2/JAK2 mutant B-ALLs and used a pharmacogenomics approach to delineate the functional role of JAK2 in these leukemias and human CRLF2-rearranged/JAK2I682F-expressing MHH-CALL4 B-ALLs." (PMID 29907650, 2018). "Here, we developed novel GEMMs of human B-ALL through transgenic overexpression of Crlf2 and concomitant expression of mutant Jak2 to determine the role of mutant JAK2 in leukemia initiation and maintenance of disease." (PMID 29907650, 2018). "Our study challenges the notion that type I JAK2is such as ruxolitinib are relatively ineffective for the treatment of CRLF2/JAK2 mutant leukemia due to paradoxical JAK2Y1007/1008 hyperphosphorylation." (PMID 29907650, 2018). "miR-375 possesses significant anti-leukemia or anti-tumor activity through modulating multiple target genes, including JAK2, SP1, PIK3CA, and AEG-1." (PMID 29439669, 2018). "Subsequent Western blot analysis of these leukemias demonstrated sustained depletion of Jak2 (lanes M4–M7), and a decrease in pStat5Y694 was observed in dsRed+ Eμ-Crlf2/Jak2P933R-pREBIR-shJak2.3323 leukemia cells harvested from moribund Dox-treated mice." (PMID 29907650, 2018). "JAK2 ubiquitination has also been reported in leukemia cells treated with a small molecule de-ubiquitinase inhibitor, WP113039." (PMID 28676638, 2017). "Despite the need for human TSLP, we and others observed engraftment of primary JAK2 mutated cells in NSG mice, giving rise to leukemia within months after intra-femoral injection." (PMID 29163799, 2017). "In this study, we found that HSP90 inhibitor (AUY922) in combination with low doses of JAK2 inhibitors (TG101209 or Ruxolitinib) led to the disassembly of the HSP90- HMWNC in IM-resistant leukemia cells and cell death." (PMID 27551334, 2016). "Both the PI3K/Akt and Jak2/Stat3 signaling have been shown to play pivotal roles in tumor cell proliferation, survival, invasion and immunosuppression in many tumors including leukemia." (PMID 27176825, 2016).
leukemia (continued). "In contrast, CUL4A, a core component of a cullin-based E3 ubiquitin ligase complex and overexpressed in cancer, and PCM1, a centrosome binding protein translocated to the JAK2 locus in certain leukemias, both bound uniquely in α7HMZ colons." (PMID 27166517, 2016). "Additional study demonstrated that more than 50% of JAK2 mutation positive MPN transforms into JAK2 mutation negative AML and is associated with much shorter interval between MPN diagnosis and leukemia transformation (3 versus 10 years)." (PMID 27752371, 2016). "Recently, we reported a role for G9a as a negative regulator in JAK2 transcription during leukemia cell differentiation." (PMID 25765655, 2015). "The constitutive activation of JAK2 has been detected in many malignant solid tumors, such as colon cancer, head and neck cancer, leukemia, multiple myeloma, and other blood diseases." (PMID 26366417, 2015). "This again relativizes the possible benefit of JAK2 inhibition in BCR-ABL1+ leukemia, as the kinase is a critical factor in normal hematopoiesis." (PMID 25333255, 2014). "MAC-1/2A/2B - the first JAK2–translocation leukemia/lymphoma cell lines described - display conspicuous JAK/STAT signalling accompanied by T-cell developmental and autoimmune disease gene expression signatures, confirming their fitness as CTCL disease models." (PMID 23372669, 2013). "Icaritin both reduced Jak-2, p-Stat3 and p-Akt expression at a dose- and time-dependent manner, suggesting that Icaritin also disturbs Jak2/Stat3/Akt signal pathway and facilitates the growth-arrest of leukemia cells." (PMID 21887305, 2011). "This study aimed to investigate the anticancer potential of three tetracycline analogues chemically modified tetracycline-3 (COL-3), doxycycline (DOX), and minocycline (MIN) in leukemia models, with a particular focus on their cytotoxic effects and modulation of the JAK2/STAT3 signaling pathway." (PMID 42076067, 2026). "Within our given follow-up, we did not detect a significant difference in overall survival or leukemia-free survival between JAK2- and CALR-mutated patients." (PMID 41463191, 2025). "Targeting the immunosuppressive components of the TME, such as Tregs, MDSCs, and angiogenesis in combination with JAK2 inhibitors, may provide a more comprehensive approach to eliminating leukemia and improving response rates." (PMID 40486651, 2025). "The dysregulation of the JAK2 signaling pathway not only drives malignant transformation but also facilitates interactions with the bone marrow microenvironment, creating a niche that supports leukemia cell survival and immune evasion." (PMID 40486651, 2025). "Strategies that block immune checkpoint molecules such as PD-1 or CTLA-4 may also synergize with JAK2 inhibitors, enhancing immune-mediated leukemia elimination." (PMID 40486651, 2025). "For example, combining JAK2 inhibitors with immune checkpoint inhibitors such as anti-PD-1 or anti-CTLA-4 antibodies could enhance the immune response against leukemia cells." (PMID 40486651, 2025). "Combining JAK2 inhibitors with BCL-2 inhibitors such as venetoclax could synergistically enhance leukemia cell death by both disrupting survival signaling (via JAK2 inhibition) and promoting apoptosis (via BCL-2 inhibition)." (PMID 40486651, 2025). "Epigenetic dysregulation in pediatric leukemia may affect key genes involved in apoptosis, DNA repair, and cell cycle regulation, making combination therapies with JAK2 inhibitors an attractive strategy." (PMID 40486651, 2025). "By combining JAK2 inhibitors with immunotherapeutic strategies, it may be possible to re-sensitize leukemia cells to immune attack and enhance the efficacy of immune-based therapies." (PMID 40486651, 2025). "In pediatric leukemia, JAK2 inhibitors could be particularly valuable for patients with JAK2 mutations or dysregulated JAK-STAT signaling, such as those with ALL, AML, and CML." (PMID 40486651, 2025).